U6 (U6 spliceosomal RNA )
Synonyms: LOC124905067
Gene: Small nuclear RNA gene on chromosome 21 (28,743,208 to 28,743,291, forward strand). Ensembl gene ENSG00000283300.
Gene Ontology:
Molecular function: U4 snRNA binding
Biological process: formation of quadruple SL/U4/U5/U6 snRNP; spliceosomal tri-snRNP complex assembly
Cellular component: U4/U6 x U5 tri-snRNP complex; U6 snRNP
Homologues: Orthologues: chimpanzee U6 (99% identical), macaque U6 (94% identical), dog U6 (69% identical), mouse Gm25147 (61% identical). Paralogues in human: RNU6-1124P (83% identical), RNU6-140P (83% identical), RNU6-28P (83% identical), RNU6-29P (83% identical), RNU6-403P (83% identical), RNU6-1117P (82% identical), RNU6-199P (82% identical), RNU6-246P (82% identical), RNU6-25P (82% identical), RNU6-33P (82% identical), RNU6-38P (82% identical), RNU6-42P (82% identical), and 1287 more.